SMC2 (structural maintenance of chromosomes 2)
Description:
Central component of the condensin complex, a complex required for conversion of interphase chromatin into mitotic-like condense chromosomes. The condensin complex probably introduces positive supercoils into relaxed DNA in the presence of type I topoisomerases and converts nicked DNA into positive knotted forms in the presence of type II topoisomerases.
Synonyms: SMC-2; hCAP-E; CAPE; SMC2L1; CAP-E
Tractability: PROTAC: ubiquitination databases record sites on it; its protein half-life has been measured; a small molecule that binds it is known.
Gene: Protein-coding gene on chromosome 9 (104,093,695 to 104,144,486, forward strand). Ensembl gene ENSG00000136824.
Subcellular location: Nucleus; Cytoplasm; Chromosome
Subcellular location (Human Protein Atlas): Nucleoplasm; Nucleoli
Pathways (Reactome):
Cell Cycle: Condensation of Prometaphase Chromosomes; Condensation of Prophase Chromosomes
Gene Ontology:
Molecular function: protein binding; chromatin binding; ATP binding; ATP hydrolysis activity; single-stranded DNA binding
Biological process: mitotic chromosome condensation; positive regulation of chromosome condensation; B cell differentiation; cell development; cerebral cortex development; chromosome organization; immunoglobulin heavy chain V-D-J recombination; positive regulation of chromosome segregation; positive regulation of chromosome separation
Cellular component: condensed chromosome; condensin complex; cytoplasm; extracellular exosome; nuclear chromosome; nucleolus; nucleoplasm; nucleus; chromatin; cytosol; chromosome; condensed nuclear chromosome
Genetic constraint (gnomAD): Loss-of-function variants: 26 observed, 88.48 expected, observed/expected ratio (o/e) 0.29, 90% interval 0.21 to 0.41. The upper end of that interval is the gene's LOEUF score, 0.41, which puts it in group 1 of 6, group 1 being the genes least tolerant of losing a copy. Missense variants: 976 observed, 1,062.9 expected, observed/expected ratio (o/e) 0.92, 90% interval 0.87 to 0.97. Synonymous variants: 343 observed, 361.37 expected, observed/expected ratio (o/e) 0.95, 90% interval 0.87 to 1.04.
Homologues: Orthologues: chimpanzee SMC2 (99% identical), dog SMC2 (96% identical), macaque SMC2 (95% identical), pig SMC2 (95% identical), rat Smc2 (93% identical), mouse Smc2 (92% identical), rabbit SMC2 (91% identical), guinea pig SMC2 (91% identical), tropical clawed frog smc2 (82% identical), zebrafish smc2 (74% identical), Drosophila melanogaster SMC2 (40% identical), Caenorhabditis elegans mix-1 (32% identical). Paralogues in human: SMC1A (20% identical), SMC1B (20% identical), SMC3 (20% identical), SMC4 (18% identical), CCDC157 (8% identical), CKAP4 (8% identical), CCDC122 (4% identical).
Diseases named in the same sentence as SMC2 in open-access papers:
SMC2 is named in the same sentence as 45 diseases in open-access papers, as found by Europe PMC text mining. Sharing a sentence is not in itself a finding about the gene and the disease. The quoted sentences say what the papers report.
colorectal cancer (9 papers, 2014 to 2025). A primary or metastatic malignant neoplasm that affects the colon or rectum. "Concretely, SMC2 gene is frameshift mutated because of mononucleotide repeats and this causes loss of its expression in colorectal cancer with high microsatellite instability (MSI-H)." (PMID 34557090, 2021). "SMC2 gene is exclusively altered by both frameshift mutation and loss of expression in gastric cancers and colorectal cancers with high microsatellite instability." (PMID 29467813, 2018). "Of note, SMC2 has been found to be over-expressed in a significant number of patients with colorectal cancer, gastric cancer, lymphoma, and some types of neuroblastoma." (PMID 41203590, 2025). "For instance, SMC2 gene knockdown was shown to suppress tumor growth in colorectal cancer, and its mRNA expression levels are notably higher in human pancreatic cancer tissue compared to non-tumor tissue." (PMID 39272991, 2024). "SMC2 gene knockdown prevents growth of colorectal cancer, and can also increase neuroblastoma cell apoptosis." (PMID 33460400, 2020). "Of note, SMC2 has been found to be over-expressed in a significant number of patients with colorectal cancer, gastric cancer, lymphoma and some types of neuroblastoma, and has been suggested as a risk biomarker in pancreatic cancers." (PMID 32098204, 2020). "In particular, SMC2 has been shown to be dysregulated or mutated in pyothorax-associated lymphoma (PAL), MYCN-amplified neuroblastoma, gastric and colorectal cancers." (PMID 29467813, 2018). "It has recently been reported that SMC2 is overexpressed in colorectal cancer or neuroblastoma cells." (PMID 25474630, 2014). "In addition, when SMC2 expression is knocked down, tumor growth is significantly reduced in a mouse model of colorectal cancer." (PMID 41203590, 2025). "In the HMF colorectal cancers, we discovered eight predictive gene deficiency models (MSH3, SMC2, SMC6, BMPR2, CLASP2, SRCAP, UBR5, and UVRAG) of monoallelic LOF with PR-AUC-E ranging from 0.21 (CLASP2) to 0.62 (MSH3) (AUROC ranging from 0.68 for SRCAP deficiency to 0.94 for MSH3 deficiency)." (PMID 36883553, 2023). "Previous reports showed that knocking down the SMC2 gene could inhibit tumor growth in colorectal cancer and increase apoptosis of neuroblastoma cells." (PMID 33460400, 2020). "Moreover, when SMC2 expression was knocked down it drastically reduced tumor growth in colorectal cancer mice models." (PMID 32098204, 2020).
neuroblastoma (8 papers, 2014 to 2025). Neuroblastoma (NB) is the most common solid, extracranial childhood tumor. "Supporting this postulate, SMC2 expression is suppressed within 6 h of THZ1 exposure of neuroblastoma cells and we found that SMC2 expression is repressed as early as 12 h following THZ1 treatment in TNBC cells (data not shown)." (PMID 37201585, 2023). "SMC2 expression is elevated in MYCN-amplified human neuroblastoma cells and down regulation of SMC2 induced DNA damage and apoptosis in human neuroblastoma cells." (PMID 29467813, 2018). "Similarly, the depletion of Smc2, and hence the reduction of both condensin I and II, in a human neuroblastoma cell line modifies the expression of a large number of genes implicated mainly in cell cycle progression or DNA damage response." (PMID 30230473, 2018). "More importantly, Yoko’s study has found that SMC2 was transcriptionally regulated by MYCN, a carcinogenic gene with poor prognosis in MYCN-amplified neuroblastoma cells." (PMID 32586319, 2020).
breast carcinoma (7 papers, 2009 to 2023). "While rs7872034 is in high LD (r2 = 0.98) with a known breast cancer risk variant (rs4742903; SMC2 intron), it may also increase the risk of developing multiple cancers." (PMID 36199081, 2022). "Notably, increased SMC2 expression is associated with poor outcomes in patients with breast cancer, suggesting that modulation of SMC2 by CDK7 or other factors may have significant impact on the aggressiveness of this disease." (PMID 37201585, 2023). "The top predicted pan-cancer regulators including RSL1D1, DDX21 and SMC2, were experimentally validated in lung, colon, breast cancer and fetal kidney cells." (PMID 38102665, 2023). "For example, we identified two variants, rs7872034 (missense variant in SMC2) and rs143745791 (missense variant in NCBP1), suggestively associated with a diagnosis of at least one breast cancer (plus any other cancer) versus no cancer." (PMID 36199081, 2022).
bladder cancer (3 papers, 2021 to 2022). "The deletion of SMC2, which is highly expressed in bladder cancer tissues, blocks the G2/M phase of bladder cancer cells, thereby inhibiting tumor growth." (PMID 34527684, 2021). "SMC2, when overexpressed, functions as an oncogene in bladder cancer." (PMID 35372377, 2022).
colon carcinoma (3 papers, 2020 to 2023). "Consistent with this, inhibition of tumorsphere formation in colon cancer cell lines was observed recently when SMC2 was inhibited by intracellular delivery of specific anti-SMC2 antibodies (Ab-SMC2) alone or with anticancer drug by polymeric micelles (PM)." (PMID 34557090, 2021). "Importantly, scaffolding the Ab-SMC2 onto nanoparticles allowed its cellular internalization and highly increased its efficacy in terms of cytotoxicity and inhibition of tumorsphere formation in MDA-MB-231 and HCT116 breast and colon cancer cell lines, respectively." (PMID 32098204, 2020).
lymphoma (3 papers, 2009 to 2025). A malignant (clonal) proliferation of B- lymphocytes or T- lymphocytes which involves the lymph nodes, bone marrow and/or extranodal sites. "In patients with pyothorax-associated lymphoma, loss-of-function mutations in SMC2 and SMC4 are associated with abnormal mitosis and genomic instability." (PMID 35916925, 2022).
ovarian carcinoma (3 papers, 2019 to 2022). A malignant neoplasm originating from the surface ovarian epithelium. "Using chromMAGMA NMOC as an example, a significant promoter (P-value 4.3 × 10−8) at a known breast and ovarian cancer genome-wide significant risk locus at chromosome 9q31 is assigned to SMC2, whereas in MAGMA, SMC2 is not significant (P-value 1.9 × 10−3)." (PMID 35777959, 2022).
microcephaly (2 papers, 2023 to 2024). A congenital or acquired developmental disorder in which the circumference of the head is smaller than normal for the person's age and sex. "The three known SMC complexes (SMC1/3, SMC2/4, and SMC5/6) function in diverse roles in DNA replication and repair, but all have been associated with microcephaly due to abnormal neurodevelopment." (PMID 38203602, 2023).
pancreatic cancer (2 papers, 2020 to 2024). "Several reports indicated that high expression of SMC2 mRNA in human pancreatic cancer tissues than in adjacent non-neoplastic pancreas tissues." (PMID 33460400, 2020). "Studies have also shown that the level of expression of SMC2 mRNA in human pancreatic cancer tissue is clearly higher than in the corresponding non-tumor tissue." (PMID 33460400, 2020). "There are several reports indicating that the expression level of SMC2 mRNA in human pancreatic cancer is significantly higher than in adjacent non-tumor tissues." (PMID 33460400, 2020).
age-related macular degeneration (1 paper, 2021). Age-related loss of vision in the central portion of the retina (macula), secondary to retinal degeneration. "WEE1, SMC2, HMGB1, RRM2, and POLA1 proteins were also observed to be involved in the progression and invasion of retinoblastoma; SLC24A2 and DTX4 in age-related macular degeneration; and EPHB6, EFNB3, and SHC1 in glaucoma." (PMID 34646884, 2021).
Cornelia de Lange syndrome (1 paper, 2023). A rare syndrome characterized by low birth weight, delayed growth, intellectual disabillity, behavioral problems, and a distinctive facial appearance (thin, arched eyebrows, low set ears, small teeth, and small nose). "Growth retardation, craniofacial anomalies, microbrachycephaly and reduced body fat have been described in cohesinopathies such as Cornelia de Lange syndrome CdLS, which is inherited in an autosomal dominant (NIPBL, SMC2 or RAD21) or X‐linked (SMC1A or HDAC8) pattern." (PMID 36627765, 2023).
cystic fibrosis (1 paper, 2017). Autosomal recessive disorder caused by pathogenic variants in the CFTR gene (cystic fibrosis transmembrane conductance regulator), which encodes a chloride and bicarbonate channel expressed in epithelial cells, and follow the diagnosis criteria. "Each of the phylogroups Smc1 to Smc4 currently holds ecologically coherent groups of strains: Smc1 and Smc2 contain exclusively Mexican river isolates recovered in this study, Smc3 groups cystic fibrosis isolates and Smc4 predominately rhizosphere isolates from diverse plants and parts of the world." (PMID 28861062, 2017).
fibrosarcoma (1 paper, 2020). A malignant mesenchymal fibroblastic neoplasm affecting the soft tissue and bone. "Also in the Detwiller datasets, SMC2 was overexpressed in fibrosarcoma, lieomyosarcoma, malignant fibrous histiocytoma, round cell liposarcoma and synovial sarcoma (6.272-, 6.259-, 8.267-, 3.615-, and 3.147-fold increases, respectively, compared to normal samples)." (PMID 33460400, 2020).
intestinal tumour (1 paper, 2022). "The SMC2 gene is a Wnt signalling target, and miRNA silencing of SMC2 reduces intestinal tumour cell proliferation." (PMID 35842572, 2022).
leiomyosarcoma (1 paper, 2020). An uncommon, aggressive malignant smooth muscle neoplasm, usually occurring in post-menopausal women. "The Barretina datasets also indicated that the expression of SMC2 was increased 3.937-, 3.049-, 2.160- and 2.358-fold in mucinous fibrosarcoma, pleomorphic liposarcoma, circular cell liposarcoma and leiomyosarcoma, respectively." (PMID 33460400, 2020).
leukemia (1 paper, 2014). A malignant (clonal) hematologic disorder, involving hematopoietic stem cells and characterized by the presence of primitive or atypical myeloid or lymphoid cells in the bone marrow and the blood. "Finally, knockdown of HLA-DRA in THP-1 leukemia cells, LNX2 in BDCM cells, and SMC2 and RIS1 in both THP1 and BDCM cells also desensitized the cells to AraC, results that were also consistent with our association results." (PMID 24483146, 2014).
malaria (1 paper, 2020). Malaria is a serious and sometimes fatal disease caused by a parasite that commonly infects a certain type of mosquito which feeds on humans. "Here we describe the structure, localization, and functional role of the condensin core subunits (SMC2/SMC4) in the mouse malaria-causing parasite P. berghei using MD, live cell imaging, ChIP-seq, protein pull-down, and conditional gene knockdown approaches." (PMID 32049018, 2020).
osteosarcoma (1 paper, 2023). A usually aggressive malignant bone-forming mesenchymal neoplasm, predominantly affecting adolescents and young adults. "Eight out of the 54 hub‐genes (ASPM, CENPF, KIF14, KIF20A, RCC1, SMC2, SRC, and TOP2A) were significantly decreased after NACT (criteria: |fold change| ≥ 2 and adjusted p value < 0.05), consistent with the central role of these hub genes in osteosarcoma." (PMID 37457661, 2023).
Patent ductus arteriosus (1 paper, 2013). In utero, the ductus arteriosus (DA) serves to divert ventricular output away from the lungs and toward the placenta by connecting the main pulmonary artery to the descending aorta. "Loss of the SMC2 population, independent of the presence of melanocytes, is therefore a cause of patent ductus arteriosus and premature death in the first months of life." (PMID 23382837, 2013).
retinoblastoma (1 paper, 2021). A malignant tumor that originates in the nuclear layer of the retina. "As shown in the protein network plot for retinoblastoma-related genes, SMC2, HMGB1, WEE1, RRM2, and POLA1 proteins showed an association with other proteins." (PMID 34646884, 2021). "The STRING database plotted their protein network, and the five proteins WEE1, SMC2, HMGB1, RRM2, and POLA1 that were most associated with the range of activity involved in tumorigenesis and retinoblastoma progression were selected from 366 genes." (PMID 34646884, 2021).
sarcoma (1 paper, 2020). A usually aggressive malignant neoplasm of the soft tissue or bone. "Accordingly, increased expression of SMC2 in sarcoma patients was associated with poor OS, in agreement with the role of SMC2 as an oncogene." (PMID 33460400, 2020). "Cells harboring SMC2 mutations indicated features with chromosomal destabilization as well, suggesting that impairment of condensin functions by somatic mutation of SMC2 might induce genome instability and contribute to the occurrence and progress of sarcoma." (PMID 33460400, 2020). "In the present study, it was found that the expression of SMC2 in sarcoma was higher than in normal tissues, which was further confirmed using IHC." (PMID 33460400, 2020). "Additionally, the prognostic value of SMC2 in sarcoma patients was determined by using the GEPIA datasets." (PMID 33460400, 2020). "Therefore, high expression SMC1A and SMC2 is potentially prognostic for sarcoma." (PMID 33460400, 2020). "Additionally, strong expression of SMC2 was significantly related to poor OS in sarcoma (p<0.05)." (PMID 33460400, 2020). "Emerging evidence showed that SMC2 knockdown may suppress growth of sarcoma and increase apoptosis." (PMID 33460400, 2020). "We concluded that SMC1A, SMC2, SMC3, SMC4, SMC5 and SMC6 were all highly expressed in sarcoma cell lines." (PMID 33460400, 2020). "According to the Cancer Cell Line Encyclopedia (CCLE), SMC1A, SMC2, SMC3, SMC4, SMC5 and SMC6 are also highly expressed in sarcoma cell lines." (PMID 33460400, 2020). "GEPIA was used to investigate the prognostic ability of SMC1, SMC2, SMC3, SMC4, SMC5 and SMC6 expression in sarcoma." (PMID 33460400, 2020). "It was confirmed that the expression levels of SMC1A, SMC2, SMC3, SMC4, SMC5 and SMC6 in sarcoma were higher than in normal tissues." (PMID 33460400, 2020). "Our results also suggest that SMC1A and SMC2 are potential therapeutic targets for sarcoma, while levels of transcripts of SMC3, SMC4, SMC5 and SMC6 are potential prognostic markers to improve the survival rate and prognostic accuracy of sarcoma." (PMID 33460400, 2020). "We found that increased expression of SMC1A, SMC2, SMC3, SMC4, SMC5 and SMC6 might play a significant role in sarcoma tumorigenesis." (PMID 33460400, 2020). "However, only the overexpression of SMC1A and SMC2 was related to the OS of sarcoma patients, whereas SMC3, SMC4, SMC5 and SMC6 had no significant impact on prognosis." (PMID 33460400, 2020).
synovial sarcoma (1 paper, 2020). "This revealed that SMC1A, SMC2, SMC3, SMC4, SMC5 and SMC6 proteins were all more highly expressed in the synovial sarcoma tissues than in corresponding normal tissues." (PMID 33460400, 2020).